ADA (adenosine deaminase)
Diseases named in the same sentence as ADA in open-access papers (continued):
Sharing a sentence is not in itself a finding about the gene and the disease.
meningitis (20 papers, 2006 to 2025). A disorder characterized by acute inflammation of the meninges of the brain and/or spinal cord. "We measured ADA (adenosine deaminase) levels using spectrophotometric method in the CSF of HIV patients with meningitis to differentiate Tuberculous meningitis from meningitis due to other causes." (PMID 27144055, 2016). "Levels of ADA in the CSF of patients with TBM were significantly higher than those in patients with meningitis due to other causes." (PMID 27144055, 2016). "Diagnostic accuracy of cerebrospinal fluid adenosine deaminase in tubercular meningitis." (PMID 39280394, 2024). "The measurements of salivary ADA activity showed significantly higher activity levels in pigs with meningitis caused by S. suis (median 12,480 U/L, minimum–maximum range 4928–35,360 U/L) compared with healthy pigs (median 1072 U/L, minimum–maximum range 281.6–3008 U/L) (p < 0.001)." (PMID 36430174, 2022). "Although ADA ≥10 IU/L has approximately 85% sensitivity and 90% specificity for diagnosing TBM, elevated ADA levels also occur in other types of meningitis, including viral (18%) and bacterial (7%) cases, necessitating PCR confirmation for accurate diagnosis." (PMID 40416201, 2025). "In this line, in pigs with meningitis, there is an increase in ADA, probably due to the stimulation of T lymphocytes, as has been previously reported in pigs." (PMID 40573424, 2025). "Keywords for the search were CSF OR cerebrospinal fluid AND ADA OR adenosine deaminase AND Mycobacterium tuberculosis OR tuberculous AND meningitis AND sensitivity." (PMID 37404432, 2023). "Adult studies have shown increased levels of adenosine deaminase (ADA) in pleural TB and TB-caused meningitis, both paucibacillary forms of TB, and have advocated its use in diagnosis." (PMID 22529869, 2012). "CSF ADA levels help differentiate TBM from other meningitis types in adults." (PMID 41181321, 2025). "Adenosine deaminase (ADA) was selected for validation using a spectrophotometric assay and demonstrated excellent performance in the differentiation between healthy and pigs with meningitis due to S. suis." (PMID 36430174, 2022). "The increased ADA abundances in the saliva of pigs with meningitis could be due to the immune activation produced by the S. suis infection." (PMID 36430174, 2022). "The study concludes that diagnostic accuracy of CSF ADA in detecting TBM is high (71.32%) which proposed it as an investigation to differentiate it from other causes of meningitis in places where PCR test is not available." (PMID 30344579, 2018). "The study concludes that diagnostic accuracy of CSF ADA in detecting TBM is high which is proposed as an investigation to differentiate it from other causes of meningitis in places where PCR test is not available." (PMID 30344579, 2018). "Thus, CSF ADA levels measurement may be a rapid and important test to differentiate TBM from other causes of meningitis." (PMID 27144055, 2016). "In addition, there is overlap with ADA activity in some pyogenic meningitis patients." (PMID 16571142, 2006). "Our findings highlight the importance of specific CSF parameters such as ADA, protein, and TLC in diagnosing meningitis." (PMID 39280394, 2024). "Another indirect test such as adenosine deaminase (ADA) test has considerable evidence to support its use for diagnosis of pleural TB and to a slightly lesser extent for TB meningitis." (PMID 27182275, 2016). "ADA assays may be useful in identifying TBM, but raised levels may also be seen in other central nervous system diseases such as purulent meningitis." (PMID 35531329, 2022). "Therefore, if meningitis is suspected, not only bacterial meningitis but also TBM should be considered and CSF analysis must include ADA, mycobacterial culture and PCR." (PMID 35371494, 2022). "The CSF ADA activity from TBM patients was compared with CSF ADA from non-TBM infectious meningitis patients, and from patients with non-infectious neurological disorders." (PMID 16571142, 2006).
meningitis (continued). "Considering that both humoral and cell-mediated immunity play an important role in TBM infection, it has been suggested that ADA activity in CSF may help differentiate TBM from non-TBM infectious meningitis." (PMID 21629544, 2010). "The mean ADA activity (with range) in the CSF of TBM patients (n = 117), non-TBM infectious meningitis patients (n = 60) and control patients with non-infectious neurological disorders (n = 104)." (PMID 16571142, 2006). "In this paper we describe a prospective study to evaluate the reliability of ADA activity in the CSF for diagnosis in patients with TBM, patients with non-TBM infectious meningitis and patients with non-infectious neurological disease." (PMID 16571142, 2006). "The mean ADA activity in TBM patients was 14.31 ± 3.87 (2.99–26.94), significantly higher than the non-TBM infectious meningitis group, 9.25 ± 2.14 (4.99–13.96); P < 0.0001, and also higher than the non-infectious neurological disorders group, 2.71 ± 1.96 (0.00–7.68); P < 0.0001." (PMID 16571142, 2006).
lymphopenia (19 papers, 2012 to 2025). Reduction in the number of lymphocytes. "We report a unique case of a three-week-old neonate who presented with prolonged and severe SARS-CoV-2 infection associated with persistent lymphopenia, subsequently revealing ADA-deficient SCID." (PMID 38711702, 2024). "In adenosine deaminase deficiency, intra-cellular accumulation of deoxyadenosine triphosphate was the cause of lymphopenia." (PMID 37208598, 2023). "ADA-deficient patients suffer from lymphopenia, severely impaired cellular and humoral immune function, failure to thrive, and a rapidly fatal course due to infection." (PMID 22969765, 2012). "Lymphopenia was also seen in the peripheral circulation, confirming that this model of ADA deficiency exhibits a SCID phenotype." (PMID 22969765, 2012). "Therefore, since ADA deficiency is characterized by T- and B-cell lymphopenia, the consequent effect of this on the RANKL/OPG axis implicates an immune-dependent process that can lead to bony abnormalities." (PMID 27579027, 2016). "While ADA is anchored in lymphocytic activation, SII captures the broader interplay of neutrophilia, thrombocytosis, and relative lymphopenia—hallmarks of TB-induced immune dysregulation." (PMID 40572784, 2025). "Blood tests at admission revealed leukopenia, particularly lymphopenia, thrombocytopenia, elevated liver enzymes, increased lactic dehydrogenase (LDH), elevated ferritin, elevated adenosine deaminase (ADA), and prolonged activated partial thromboplastin time." (PMID 39797188, 2024). "Similar results have been shown in untreated ADA-SCID patients, whereby, despite peripheral lymphopenia, only a partial block in B-cell development is demonstrated within the bone marrow." (PMID 27579027, 2016).
X-linked SCID (17 papers, 2011 to 2023). "Mutations in a number of genes can cause SCID: The IL2R-gamma gene mutations cause X-linked SCID; mutations in Adenosine Deaminase ADA-SCID and mutations in either of the Recombinase Activating Genes RAG-SCID." (PMID 32545727, 2020). "Currently, the use of self-inactivating lentiviral vectors has shown good promise as a safe and effective platform for HSC gene therapy, as demonstrated in clinical trials for X-linked SCID, adenosine deaminase (ADA)-deficient SCID, Fanconi anemia (FA), CGD and WAS." (PMID 36091069, 2022). "Gene therapy is currently tested in clinical trials for ADA-SCID, X-linked SCID, Artemis SCID and RAG1 SCID." (PMID 37846903, 2023). "Gene therapy for X-linked SCID and for adenosine deaminase-deficient SCID has been established, with a licensed vector for adenosine deaminase-deficient SCID available in Europe." (PMID 30800289, 2019).
pulmonary TB (16 papers, 2012 to 2026). "There was a significant association found between raised ADA levels and pulmonary tuberculosis (p < 0.05)." (PMID 31016096, 2019). "There was a significant association found between raised ADA levels and pulmonary TB (p = 0.015)." (PMID 31016096, 2019). "Male sex is a significant risk factor for TE while the presence of pulmonary TB is protective, and high levels of pleural ADA and WBC count could aid in early diagnosis of TE." (PMID 31863026, 2019). "Compared to previously studied or emerging biomarkers in pulmonary tuberculosis—such as lymphokine panels or serum proteomic profiles used primarily to differentiate active disease from latent TB infection, ADA remains a compelling candidate." (PMID 40572784, 2025). "Recently, more studies proposed serum ADA level measurements as a useful marker for diagnosing cases of pulmonary TB when bacteriological confirmation is missing." (PMID 40572784, 2025). "Background and Objectives: The role of adenosine deaminase (ADA) in pulmonary tuberculosis (PTB) remains insufficiently defined in advanced forms of disease." (PMID 40572784, 2025). "Previous studies have also reported raised serum ADA levels in pulmonary TB and EPTB, however, information about the proportion of cases with raised levels is not always given." (PMID 39623309, 2024). "Raised ADA levels have been also reported to decrease with successful treatment in pulmonary TB patients, however, there is a paucity of literature on the role of ADA in monitoring treatment response in EPTB." (PMID 39623309, 2024). "According to the best of our knowledge much less data are available in medical literature from developing world regarding ADA levels in pulmonary TB." (PMID 31016096, 2019). "Adenosine deaminase level is an important marker for diagnosis of pulmonary TB in lymphocytic pleural effusion." (PMID 31016096, 2019). "The binary logistic model was also performed to ascertain the effects of pulmonary TB on the likelihood of raised ADA levels in patients with lymphocytic pleural effusions." (PMID 31016096, 2019). "Several studies were carried out, have suggested the use of serum ADA levels for the diagnosis of pulmonary tuberculosis." (PMID 24319523, 2013). "Adenosine deaminase (ADA) has also been extensively evaluated in the body fluids of pulmonary TB (PTB) and extra pulmonary TB (EPTB) patients with reliable sensitivity and specificity." (PMID 24069327, 2013). "Due to this evidence, a serum ADA has already been evaluated in a childhood population with a very high sensitivity (100%) and specificity (90.7%) for pulmonary TB." (PMID 22529869, 2012). "However, serum ADA levels have received less attention in advanced pulmonary TB despite being a rapid, cost-effective, and reliable diagnostic tool suitable for laboratories with limited resources." (PMID 40572784, 2025). "Furthermore, most of the studies demonstrating raised levels of ferritin, CRP, and ADA in TB and a decrease with treatment have focused on pulmonary TB with relatively few reports on these markers in EPTB cases." (PMID 39623309, 2024). "The ADA levels are 12 times likely to be raised in pulmonary TB." (PMID 31016096, 2019). "While several studies have explored serum ADA levels in PTB patients versus healthy controls, there is a notable paucity of data specifically addressing its prognostic value in advanced pulmonary tuberculosis, particularly in relation to earlier disease stages." (PMID 40572784, 2025). "In the present case, although the cell count, glucose level, and protein concentration were normal, ADA levels were high which prompt us to think of other investigative tools to rule out CNS‐TB in this child with stroke and pulmonary TB." (PMID 36789297, 2023).
Autoimmunity (15 papers, 2009 to 2025). The occurrence of an immune reaction against the organism's own cells or tissues. "Long-term morbidity in patients with ADA deficiency, particularly autoimmunity and neurodevelopmental outcomes, is an area which requires further study." (PMID 35288820, 2022). "Intriguingly, mutations in the adenosine deaminase ADAR1 can confer autoimmunity in humans and in mice models and recently ADAR1 has been shown to regulate the canonical RLR-, PKR-, and OAS-RNAse L pathways." (PMID 31404141, 2019). "Additionally, mutations or deficiencies in adenosine deaminase, an essential enzyme for purine degradation or salvage, increase susceptibility to infections and autoimmunity." (PMID 39466737, 2024). "Nucleic acid-sensing TLRs might therefore represent Achilles’ heel in susceptible ADA-deficient patients by which relative tolerance for nucleic acid-containing antigens is breached and autoimmunity occurs." (PMID 22969765, 2012). "A skewed repertoire and decreased immune functions have been implicated in autoimmunity observed in certain B-cell and/or T-cell immunodeficiencies, but it remains unclear to what extent specific mechanisms of tolerance are affected in ADA deficiency." (PMID 22969765, 2012). "Recent in-depth studies have revealed specific defects in ADA deficiency that may contribute to the onset of autoimmunity in these patients." (PMID 22969765, 2012). "The strong overlap of autoimmune manifestations observed in this model of autoimmunity in ADA−/− mice with those reported in ADA-deficient patients suggests that a component of autoimmune susceptibility may map to the target tissue." (PMID 22969765, 2012). "Also, mutation or deficiency of adenosine deaminase, which is a key enzyme for purine metabolite degradation or salvage into the nucleotide pool, increases susceptibility to infections and autoimmunity, and adenosine deaminase activity has been used as a diagnostic marker for cancers." (PMID 30105018, 2018). "It is likely that reduced ADA activity serves as a core factor, and combination of ADA with autoimmunity-dependent injury and direct liver injury leads to manifestation of IPH." (PMID 26549939, 2015). "Although autoimmune manifestations are frequent findings in ADA-deficient patients with milder forms or in patients under PEG-ADA, mechanisms causing the loss of peripheral tolerance and onset of autoimmunity have remained elusive." (PMID 22969765, 2012). "However, in this ADA-deficient cohort, neither alemtuzumab nor GvHD was associated with autoimmunity, but numbers of affected patients in this report are too small to draw any definitive conclusions." (PMID 35288820, 2022). "Indeed, anemia is not a typical feature of ADA deficiency, unless induced by autoimmunity, and monocyte numbers were previously reported as normal in most ADA-deficient patients." (PMID 34777360, 2021). "Less severe phenotypes of ADA-CID, which accounts for up to 20% of cases, are rarer than ADA-SCID, and typically present with infections or autoimmunity." (PMID 40140214, 2025). "Compared with subcluster 1 of plasma cells, subcluster 0 cells had higher levels of positive autoimmune antibodies and autoimmunity ability, with higher expression of ITPR3 and ADA." (PMID 40904455, 2025). "Recent advances indicate that the adenosine deaminase ADAR1 through RNA editing is involved in dampening the canonical antiviral RIG-I-like receptor-, PKR-, and OAS-RNAse L pathways to prevent autoimmunity." (PMID 31404141, 2019). "Since varying degrees of immune reconstitution can be achieved by the available treatment options for ADA-SCID, breakdown of tolerance and development of autoimmunity can represent a major concern." (PMID 22969765, 2012). "No specific reports on immune dysregulation or autoimmunity in BMT-treated ADA-SCID patients are available in literature." (PMID 22969765, 2012).
lung carcinoma (15 papers, 2012 to 2025). "On the other hand, decreased adenosine deaminase (ADA) levels in brochoalveolar lavage (BAL) has been used as a diagnostic biomarker for lung cancer." (PMID 36859386, 2023). "Some studies indicated that ADA, participating in encoding an enzyme involved in purine metabolism, is downregulated in lymphocytes of advanced stage lung cancer." (PMID 32953885, 2020). "The only known target gene ADA of nebularine was connected to 119 lung cancer-related genes and 117 predicted novel KDDA genes in this subnetwork." (PMID 34131148, 2021). "Serum ADA activity, as a tumor marker, is found to be increased in patients with lung cancer." (PMID 31660294, 2019). "Existing clinical biomarkers, such as adenosine deaminase (CEA) and cytokeratin (CYFRA21-1), have played a certain role in the early diagnosis of lung cancer." (PMID 40313958, 2025). "A study found ADA levels >35 U/L in 6% of noncomplicated lung cancer cases, 44% of complicated lung cancer cases, 70% of empyema cases, and 10% of malignant tumors." (PMID 39641275, 2024).
primary immunodeficiencies (15 papers, 2014 to 2025). "An equally high overrepresentation (OVF = 20.83, q-value = 2.38 × 10−6) was determined for the “magenta” module that was enriched in genes that control primary immunodeficiency, including ADA, CD19, CD79A, IGLL1, TAP1, TAP2, TNFRSF13C, and ZAP70." (PMID 32873298, 2020). "This strategy shows good response in providing treatment for adenosine deaminase-deficiency (ADA-SCID), which is a primary immunodeficiency." (PMID 28053975, 2016). "Finally, we demonstrate differential circRNA expression in ADA-SCID and WAS, two primary immunodeficiencies which are caused by mutations in ADA or WAS, respectively." (PMID 28842720, 2017). "Adding KRECs next to TRECs to the screening panel allowed for the detection and thus early treatment of delayed onset ADA-SCID and primary immunodeficiencies featuring B cell lymphopenia (e.g., XLA, NBS and possibly AT)." (PMID 25893636, 2015). "Another exemplar primary immunodeficiency is the adenosine deaminase SCID (ADA-SCID), which is characterized by the lack of ADA enzyme and accumulation of the deoxyadenosine triphosphate substrate." (PMID 28744797, 2017).
type 2 diabetes (14 papers, 2010 to 2024). "Genetically, ADA locus in chromosome 20 is associated with locus type 2 diabetes." (PMID 28050278, 2016). "Particularly, studies have shown that serum ADA activity is significantly higher in patients with uncontrolled type 2 diabetes and has a correlation with glycemic parameters." (PMID 38092892, 2023). "The aim of the present study was to evaluate the association between adenosine deaminase (ADA) levels and diabetic kidney disease (DKD) in patients with type 2 diabetes (T2D)." (PMID 34319903, 2021). "In the current study, we evaluated the association of serum ADA levels and DKD in type 2 diabetic patients." (PMID 34319903, 2021). "This is particularly intriguing because adenosine deaminase (ADA), the enzyme that catalyzes the conversion of adenosine to inosine, is known to be more active in type 2 diabetic patients and is associated with liver fibrosis in NAFLD." (PMID 33345777, 2020). "In this study we have investigated the alternation of serum ADA activities and its mechanism in type 2 diabetic patients." (PMID 28050278, 2016). "This study aimed to determine whether increased serum ADA levels are related to diabetic peripheral neuropathy (DPN) in patients with type 2 diabetes (T2D)." (PMID 36267565, 2022). "In a small network, known causal components ADA and CD26 (DPP4) form a cascade with the predicted causal component CD44 (green node) connected by RANTES (CCL5) (blue node), which harbors promoter polymorphisms associated with type 2 diabetes." (PMID 20815942, 2010). "Before the use of DPP-4 inhibitors for the treatment of type 2 diabetes, DPP-4 had been intensively studied as an immune regulator because it acts as a T cell costimulator and a binding partner of adenosine deaminase (ADA)." (PMID 25140306, 2014). "First, the present study is a cross-sectional study, which cannot conclude a cause–effect relationship between high serum ADA levels and DKD in type 2 diabetic patients." (PMID 34319903, 2021).